ERVK13-1 (endogenous retrovirus group K13 member 1)
Description:
Retroviral envelope proteins mediate receptor recognition and membrane fusion during early infection. Endogenous envelope proteins may have kept, lost or modified their original function during evolution (By similarity). SU mediates receptor recognition. TM anchors the envelope heterodimer to the viral membrane through one transmembrane domain. The other hydrophobic domain, called fusion peptide, mediates fusion of the viral membrane with the target cell membrane (By similarity).
Gene: Long non-coding RNA gene on chromosome 16 (2,608,379 to 2,682,398, reverse strand). Ensembl gene ENSG00000260565.
Subcellular location: Virion; Cell membrane (Transmembrane protein)